BATF (basic leucine zipper ATF-like transcription factor)
Diseases named in the same sentence as BATF in open-access papers (continued):
Sharing a sentence is not in itself a finding about the gene and the disease.
tumor (continued). "Notably, IL32 and BATF have been implicated in the immunosuppressive functions of tumor-infiltrating Tregs, suggesting that IL32+BATF+ Tregs in dogs may represent a regulatory subset relevant in cancer." (PMID 41488614, 2025). "Furthermore, cooperation of IRF4 and BATF could counteract T cell exhaustion and improve anti-tumor response of CAR-T cells." (PMID 38918817, 2024). "Moreover, based on the overexpression of BATF and IRF4 in exhausted T cells, knockdown of BATF or IRF4 could remarkably enhance the tumor-killing ability of CAR-T cells by reversing their exhaustion and prolonging their persistence." (PMID 36814912, 2023). "Moreover, knockdown of BATF suppresses tumor cell viability." (PMID 35573731, 2022). "The high expression of BATF may partially account for drug resistance in tumor chemotherapy." (PMID 35573731, 2022). "After observing the critical role of BATF downstream of IL-21 signaling in tumor-infiltrating effector CD8+ T cell differentiation, infiltration, and function, we wanted to explore whether BATF overexpression in tumor-specific CD8+ T cells could bypass their need for CD4+ T cell help." (PMID 33809259, 2021). "BATF overexpression reversed the inhibitory effect of SLC39A5 depletion on the behavior of GC cells and tumor growth." (PMID 40992658, 2025). "The inconsistency can be attributed to the multifaceted roles of BATF and IRF4, which can contribute to either effector or exhaustion programs depending on T cell types, tumor models, and experimental conditions." (PMID 40693464, 2025). "In particular, CAR-T cells with combined BATF and TFAP4 KI exhibited superior tumor control compared with single KIs, showing a reduction of terminally differentiated Tem cells but increased Tscm and Tcm cells." (PMID 40693464, 2025). "Differential expression levels of PTTG1 and BATF between HCC and adjacent non-tumor tissues were further validated by immunohistochemistry (IHC) in 25 patient tissue samples." (PMID 40315269, 2025). "Our previous research has shown that basic leucine zipper ATF-like transcription factor (BATF) and early growth response 1 (EGR1) play a role in chimeric antigen receptor T (CAR-T) cell exhaustion during AML tumor elimination." (PMID 40225861, 2025). "BATF and IRF4 overexpression reduced exhaustion, promoted effector functions, and enhanced tumor-infiltrating CAR-T cells." (PMID 40693464, 2025). "Cotargeting both BATF and ETS1 promoted T cell infiltration in the tumor microenvironment and induced superior effector responses." (PMID 40693464, 2025). "Moreover, CRISPR-Cas9-mediated BATF knock-out in activated Tregs informed that BATF was vital in the stimulation and survival of activated Tregs, suggesting a potential opportunity to therapeutically target tumour-associated Tregs without affecting immune homeostasis." (PMID 38581063, 2024). "Deletion of BATF in REGNASE-1-null cells hampered cell proliferation and survival and decreased IFN-γ, GZMB, and TNF-α expression, dampening anti-tumour capability." (PMID 38581063, 2024). "BATF expression was positively related to GLUT-1 expression and PET/CT parameters, including tumor size, maximum standard uptake value, metabolic tumor volume, and total lesion glycolysis." (PMID 38862971, 2024). "Nevertheless, inhibiting the interaction between BATF and IRF4 will greatly weaken the tumor control ability of BATF-overexpressing CAR-T cells." (PMID 36814912, 2023). "(2021) showed that overexpression of BATF on CAR-T cells reduced exhaustion program and increased anti-tumor immunity in murine melanoma." (PMID 37398660, 2023). "Tet2 reshapes the chromatin accessibility of several key TFs at genomic binding regions, including BATF and ETS1 in CD8+tumor-infiltrating lymphocytes, thereby enhancing its anti-tumor immune function and suppressing melanoma growth in vivo." (PMID 36203205, 2022).
tumor (continued). "The differential expression in GRNs identified in each patient also confirmed the tumor heterogeneity of SBA, with transcription factors (TFs) such as BATF, CREB3L1, KLF2, E2F1 variably expressed among different patients." (PMID 36104333, 2022). "From a mechanistic perspective, BATF was recruited to the TM4SF1 promoter by BCYRN1, and reducing the expression of this lncRNA was sufficient to constrain xenograft tumor growth in mice." (PMID 35730016, 2022). "In contrast, overexpressing BATF in CD8+ T cells enhanced effector function and resulted in improved tumor control, bypassing the need for CD4+ helper T cells." (PMID 33809259, 2021). "In this study, our data show that BATF, one of the downstream targets of IL-21 signaling, is necessary for CD8+ T cell effector differentiation and anti-tumor function." (PMID 33809259, 2021). "In this study, we found that Basic Leucine Zipper ATF-Like Transcription Factor (BATF), a transcription factor downstream of IL-21 signaling, is critical to maintain CD8+ T cell effector function within the tumor." (PMID 33809259, 2021). "Notably, compared with the PD‐L1− tumor group, the upregulated differentially expressed genes (DEGs) in the CD8‐C2‐Texterm subset from PD‐L1+ tumor group included exhaustion‐related genes such as HAVCR2, CXCL13, PDCD1, TIGIT, LAG3, BATF, GNLY, and CTLA4." (PMID 41194450, 2026). "In various types of CAR-T cells and mouse OT-1 cells, the absence of BATF rendered T cells more resistant to exhaustion and endowed them with a stronger capacity for tumor eradication." (PMID 40496561, 2025). "Studies have shown that Treg cells in the lung cancer tumor microenvironment (TME) and those in peripheral blood exhibit different chromatin landscapes, and sequencing has identified BATF as a key differentiation-related transcription factor for Treg cells in the TME." (PMID 39876010, 2025). "Considering the fact that BATF plays vital roles in CD8+ T-cells, we speculated that there are two strategies for tumor immunotherapy by focusing on BATF." (PMID 35573731, 2022). "Genes regulated by EHF_extended, BATF_extended, and CD59_extended were highly upregulated in advanced tumor cells, while genes regulated by ATF3, JUNB_extended, and FOSB_extended were upregulated in early tumor cells." (PMID 33783985, 2021). "Our work shows that the protein Basic Leucine Zipper ATF-Like Transcription Factor (BATF) may be a key regulator of CD8+ T cells and their anti-tumor function." (PMID 33809259, 2021). "Furthermore the enrichment of other transcription factors from the same cluster (BATF, PLXNC1, MTF1) as NFkB have been shown to upregulate in other cancers suggesting NFkB to exert and a pro-tumor effect." (PMID 33177572, 2020). "Transcription factor binding motif enrichment analysis identifies several immune-related transcription factors, including three exhaustion-related genes (NR4A1, BATF, and EGR2) and VDR, which potentially play an important regulatory role in tumor-reactive CD8+ T cells." (PMID 31892342, 2019). "We reasoned, therefore, that the relative expression of BATF and SPIB might contribute to heterogeneity of tumour biology among ABC-DLBCL." (PMID 24875472, 2014). "With the caveat that gene expression assessments from primary tumour samples derive from mixed cell types, this confirmed that OCI-LY3 and LY10 fell within the general distribution of expression values for BATF and IRF4, and at the high end of the SPIB distribution." (PMID 24875472, 2014). "BATF is a key factor involved in up-regulating a subset of exhaustion-related genes in CAR-T cells, and it has been demonstrated that depletion of BATF could enhance the anti-tumor activity of CAR-T cells and increase central memory CAR-T cells." (PMID 36891310, 2023). "The cooperation of BATF and IRF4 could again exhaust tumor-infiltrating CAR T cells." (PMID 37231356, 2023). "IRF and BATF negative mice had a fast rate of tumour development." (PMID 35388653, 2022).
tumor (continued). "Unlike those in immune cells, the roles of BATF have only been illustrated in limited tumor types." (PMID 35573731, 2022). "Taken together, our findings reveal that BATF overexpression bypasses the need for CD4+ T cell help and could be harnessed to provide therapeutic benefits by enhancing effector CD8+ T cell survival and anti-tumor functions." (PMID 33809259, 2021). "Recognizing that BATF is an intrinsically necessary transcription factor in CD8+ T cell infiltration/survival and function within the tumor, we wanted to test whether BATF overexpression could further enhance CD8+ T cell function and tumor control." (PMID 33809259, 2021). "Among the rich screen results, several intriguing genes (BATF, PRDM1, and TOX) and signalling cascades (JAK-STAT and NF-κB pathways) have been identified to extensively engage in multiple branches of T cell anti-tumour responses and might be leveraged to advance cancer immunotherapies." (PMID 38581063, 2024). "Basic leucine zipper ATF‐like transcription factor (BATF), involved in the synergistic induction of target gene expression, is further induced by co‐binding of STAT3 and STAT6, and high levels of BATF expressed from macrophages may contribute to tumor progression." (PMID 38098217, 2023). "Another study employed nonviral ModPoKI screening, which is combinatorial KI of BATF and TFAP4, and demonstrated effective tumor control against Nalm-6 leukemia with GD2 expression." (PMID 40693464, 2025). "Thus, because BATF is both a driver of effector differentiation and a suppressor of memory, its transcriptional circuits may be activated to generate more effector-like CD8+ T cells, or repressed to generate more memory-like CD8+ T cells, ultimately improving anti-tumour efficacy." (PMID 39399500, 2024). "Our IHC results revealed no significant expression differences between tumors and paracancers, which could suggest that BATF’s role in HCC is more related to immune regulation, particularly in T cell exhaustion rather than direct tumor cell activity." (PMID 40315269, 2025).
cancer (35 papers, 2016 to 2025). A tumor composed of atypical neoplastic, often pleomorphic cells that invade other tissues. "Yin and colleagues stratified BC patients into high and low risk cancers based on a seven gene expression assay (BATF, CD3D, HLA-DQB2, JUN, MAP2K6, NFKBIE, PAK1)." (PMID 40148963, 2025). "Recent studies have shown that across several disorders, BATF is associated with macrophage activation and cancer growth." (PMID 39872530, 2024). "An increasing body of evidence suggests that BATF-deficient CD8+ T cells display impaired effector phenotypes against cancer and infections." (PMID 38297190, 2024). "BATF (Basic Leucine Zipper ATF-Like Transcription Factor) affects the prognosis of many kinds of cancer by combining with HHLA2 (HERV-H LTR-associating 2) DNA, especially the prognosis of KIRC." (PMID 35832648, 2022). "In addition, we also observed that the expression level of BATF was associated with a number of immunomodulatory genes in the pan‐cancer species obtained from TCGA dataset." (PMID 40182138, 2025). "High expression of BATF in Treg cells is associated with poor cancer prognosis." (PMID 39876010, 2025). "Recent studies have identified BATF as a key factor in driving T cell exhaustion, especially in chronic infections and cancer, by activating exhaustion-related genes and inhibits effector T cell functions." (PMID 40315269, 2025). "By analyzing the immune landscape of NBL, we identified six genes - BATF, CXCR3, GIMAP5, GPR8, IGHM, and ISG20-with diagnostic and clinical significance in other cancers, but whose roles in NBL remain largely unexplored." (PMID 39559348, 2024). "The basal‐cancer‐specific BATF and MAFF activities were monotonically upregulated during transformation." (PMID 38582099, 2024). "The activity of GATA‐family and MEF2C TF was upregulated in luminal cancer cells, while that of the ATF (BATF/MAFK/MAFF/BACH1) TF was upregulated in basal cancer cells." (PMID 38582099, 2024). "We also explored potential roles of BATF in a pan-cancer cohort by performing immune infiltration, Gene Ontology (GO) enrichment, and the Kyoto Encyclopedia of Genes and Genomes (KEGG) analysis." (PMID 35573731, 2022). "This revealed a set of genes shared with human eTreg cells from affected sites in JIA, RA, and cancer including BATF, VDR, MICAL2, TOX2, KAT2B, PFKFB3, and IL12Rβ2." (PMID 33976194, 2021). "Thus, targeting BATF represents a promising therapeutic strategy to reverse T cell exhaustion and restore immune function in cancers like HCC." (PMID 40315269, 2025). "BATF also plays a significant role in transplant rejection and cancer treatment contexts." (PMID 39876010, 2025). "These investigations have unveiled BATF as a key regulator of T cell function, with its deletion potentially enhancing T cell persistence and antitumor activity, thereby offering new strategies for cancer immunotherapy." (PMID 40496561, 2025). "Such a pan-cancer analysis provides evidence to uncover the distinct roles of BATF in the immune microenvironment, which may be meaningful for the following functional experiments." (PMID 35573731, 2022). "However, the role of BATF in T cell exhaustion remains controversial, as recent studies supported a beneficial role of BATF on T cell responses in chronic infection and cancer." (PMID 35371563, 2022). "Among these genes, only BATF3 and IRF4 were highly co-expressed with BATF in the majority of cancers, which suggested that BATF might carry out its role by cooperating with BATF3 and IRF4." (PMID 35573731, 2022). "However, the expression and potential roles (especially immune cell infiltration) of BATF in the majority of cancers remains to be illustrated." (PMID 35573731, 2022).
cancer (continued). "To gain insights into the potential mechanisms of BATF in cancers, we performed KEGG analysis." (PMID 35573731, 2022). "After knowing the roles of BATF in immune infiltration and immune checkpoint pathway in cancer, we wondered whether there is a correlation between BATF expression and immunotherapeutic response." (PMID 35573731, 2022). "It seems that genetic alterations of BATF play a limited role in carcinomas." (PMID 35573731, 2022). "Among these genes, three (BATF, PHYHIPL, and RBP1) have been reported as cancer-associated genes." (PMID 34178621, 2021). "However, further investigations into the epigenetic mechanisms by which BATF regulates effector CD8+ differentiation in cancer remain of interest." (PMID 33809259, 2021). "In addition, BATF displayed potential immune regulatory ability across pan‐cancer." (PMID 40182138, 2025). "BATF expression could also predict immunotherapeutic and chemotherapy responses in cancers." (PMID 35573731, 2022). "In cancer models, BET(bromodomain and extra-terminal motif) inhibitors have been shown to positively impact CD8+T cells by directly inhibiting BATF, thereby enhancing the persistence of stem-like memory CD8+T cells." (PMID 39876010, 2025). "Since literature evidence supports the important roles of CD44, BATF, LGALS3, and NFKBIZ in cancer, we decided to validate the expression of these genes with independent experimental methods." (PMID 36982699, 2023). "In ESCC cell lines, we examined all AP-1 transcription factors including JUN, FOS, MAF, and ATF family members and found that FOSL1, MAFK, BATF, and ATF5 are upregulated compared to non-cancer cells." (PMID 34722266, 2021). "Our study reveals the critical role of BATF in maintaining and enhancing functional effector CD8+ T cells in response to cancer." (PMID 33809259, 2021). "We, therefore, sought to assess the CD8+ T cell-intrinsic requirement of BATF downstream of IL-21 signaling, its role in effector CD8+ T cell differentiation and function in cancer, and its utility as a potential immunotherapeutic target." (PMID 33809259, 2021). "Some of the notable increases seen in cancer patients included subsets of T cells expressing basic leucine zipper transcription factor, ATF-like (BATF), PD-L1 and CTLA-4, which are inhibitory markers involved in immune checkpoint pathways and are increased upon T cell activation." (PMID 28936253, 2016). "Moreover, calycosin inhibited the proliferation, invasion, and migration of cancer cells through decreasing MMP‐2, MMP‐9, and CD147 levels through downregulating BATF (basic leucine zipper ATF‐like transcription factor) expression and TGFβ1 (transforming growth factor 1) expression." (PMID 38230908, 2024). "Our results indicated that genetic alterations might not be crucial in the prognostic roles of BATF in cancers." (PMID 35573731, 2022). "Therefore, further investigation into potential metabolic targets of BATF may provide insight as to how BATF mediates effector CD8+ T cell survival and function in cancer." (PMID 33809259, 2021). "In addition to these five TFs, we identified BATF, SMARCB1, TAF1 and MXI1 as novel TERT regulators across cancer entities that to our knowledge, so far, have not been described in the literature as TERT regulators." (PMID 31888467, 2019).
infection (7 papers, 2018 to 2025). The state of being infected such as from the introduction of a foreign agent such as serum, vaccine, antigenic substance or organism. "An early study reported that BATF expression in human B cells significantly increased after infection with EBV, indicating its involvement in the early response to viral infection." (PMID 39876010, 2025). "On the one hand, in a mouse infection model, BATF has been shown to influence CD8+ T cell responses, and its deficiency leads to an altered induction of antiviral CD8+ T effector cells." (PMID 38297190, 2024). "Once they enter the periphery, BATF-dependent iILC2 cells can accumulate in systemic sites of infection such as the lungs to contribute to tissue repair and orchestrate the re-establishment of barrier integrity." (PMID 36052086, 2022). "However, BATF can partially compensate for the loss of BATF3, restoring dendritic cell function, especially during infections." (PMID 39876010, 2025). "For instance, following infection with Lymphocytic Choriomeningitis Virus (LCMV), the expression levels of BATF significantly increase in the infected effector CD8+T cells and persist in memory CD8+T cells." (PMID 39876010, 2025). "For example, the expression of many TFs changed significantly over the course of infection, including decreases in Fos, Jun, and BCL6, and increases in Bach2 and BATF." (PMID 33497421, 2021). "At 2 days after infection, EBV markedly induced expression of MYC, CD21, CD23, HES1, and BATF (positive controls) 10- to 20-fold, possibly through EBNA2; in contrast, host housekeeping genes including β-2 microglobulin (B2M) and RNA polymerase II (POLR2A) were unaffected." (PMID 30487153, 2018).
bacterial infections (3 papers, 2021 to 2023). "Transcription factor BATF as a key transcription factor, regulation of Treg differentiation in non-lymphoid cells, which most are used to regulate T cells in viral and bacterial infections and in tumor immunity disease, very little research has been done on cardiovascular disease." (PMID 36303246, 2022). "In addition, BATF depletion may result in defective responses from ILC2 to inflammatory cytokines during bacterial infection." (PMID 37893107, 2023). "We found three genes, namely BATF, ISG15 and DNMT1, which can distinguish viral from bacterial infections in a wide range of cohorts including different pathogens, ages and populations, and with potential to become clinical biomarkers for infectious diseases in a clinical setting." (PMID 33808774, 2021).